IL1B (interleukin 1 beta)
Diseases named in the same sentence as IL1B in open-access papers (continued):
Sharing a sentence is not in itself a finding about the gene and the disease.
gastric ulcer (continued). "It has been indicated that DAP has a protective effect on indomethacin-induced gastric ulcers in mice by targeting NF-kB, TNF-α, IL-1β, and decreasing oxidative stress biomarkers." (PMID 35949308, 2022). "PS and omeprazole supplementation significantly reduced WIRS-exposure-induced gastric ulcers and MDA, iNOS, and IL-1β levels." (PMID 36712695, 2022). "Studies have shown that inflammatory factors such as pro-inflammatory cytokines TNF-α and IL-1β are significantly up-regulated and PI3K/Akt axis is activated in mice with gastric ulcer." (PMID 33841162, 2021). "In another murine model, intravenous nesfatin-1 alleviated gastric ulcers and reduced TNF-α and IL-1β by suppressing cyclooxygenase 2 signaling." (PMID 34389003, 2021). "In the ethanol-induced gastric ulcer model, kaempferol, a flavanol from Kaempferia galanga L, decreased the plasma level of TNF-α by 33%, 43%, and 48%, and that of IL-1β by 46%, 43%, and 37% at doses of 40, 80, and 160 mg/kg, respectively." (PMID 33050668, 2020). "Through our model, we evaluated this situation during infection, where production of both IL1β and IL8 increases up to 4 times than that of normal, thus leading to inflammation induced epigenetic changes for the development of gastric ulcer and carcinoma." (PMID 28932213, 2017). "The results confirmed that DOP was effective in reducing the levels of inflammatory factors (IL-1β, IL-6, and TNF-α) in the gastric tissues of rats with gastric ulcers, with the most significant effects observed in the DOP-200 and DOP-400 groups (p < 0.05 or p < 0.01)." (PMID 38398633, 2024). "In a further study, manuka honey was also effective against chronic acetic acid-induced gastric ulcers, and the observed effect was due to antioxidant and anti-inflammatory effects with a significant reduction in mucosal MDA levels, TNF-α, IL-1β, and IL-6 and an increase in IL-10 levels." (PMID 38045104, 2023). "One of the problems related to the gastric ulcer is its capacity to recurrence, a complex process involving increased levels of inflammatory mediators, such as tumor necrosis factor (TNF) and interleukin (IL)-1β at the gastric mucosa." (PMID 35463093, 2022). "The results of this study showed that MOE could inhibit the levels of proinflammatory cytokines (TNF-α, IL-1β, IL-6) induced by ethanol, suggesting that MOE has an anti-inflammatory effect on ethanol-induced gastric ulcer." (PMID 34159200, 2021). "Indeed, IL-1β, IL-8, and PGE2 just like TNF-α promote the inflammatory response and are strongly involved in the development and maintenance of gastric ulcers in humans." (PMID 33354210, 2020). "However, the levels of TNF-α, IL-1β and IL-6 in tissue and GES-1 cell supernatant were significantly decreased, and the corresponding gastric ulcer and mucosal integrity were improved in the Ran and F-AOH groups." (PMID 32871094, 2020). "Furthermore, the serum proinflammatory cytokine IL-1β, IL-6, and TNF-α levels were significantly decreased following the administration of ethyl acetate extract of SP in a gastric ulcer model." (PMID 30116487, 2018). "Another possible mechanism by which manuka honey treats gastric ulcer may be due to inhibition of the proinflammatory cytokines: TNF-α, IL-1β, and IL-6." (PMID 28250794, 2017). "Therefore, the present study was extended to evaluate the healing effects of MSE (test drug) in acetic acid-induced gastric ulcer in diabetic (DR-AA) rat and its effects on TNF-α, IL-1β and TGF-α." (PMID 24192345, 2013). "Pro-inflammatory cytokines like tumor necrosis factor-α (TNF-α), Interleukin-1β (IL-1β), Interleukin-6 (IL-6) and growth factors including insulin like growth factor-1 (IGF-1) play an important role in the pathogenesis of chronic diseases like autoimmune diabetes and gastric ulcers." (PMID 24192345, 2013).
kidney damage (65 papers, 2012 to 2025). "Acute nephrotoxicity is closely related to inflammatory response and induces the expression of various cytokines and chemokines, and elevated cytokine levels (such as tumor necrosis factor (TNF)-α, interleukin (IL)-1β, and IL-6) are associated with kidney damage." (PMID 32916975, 2020). "Above all, scRNA‐seq analysis demonstrated that EA exerts anti‐inflammatory effects and reduces the IL‐1β expression in treating HUA‐induced nephropathy through downregulation of both the NLRP3 inflammasome and the JAK2/STAT3 signaling pathway." (PMID 41278550, 2025). "Experimental mouse models of kidney damage and fibrosis link IL-1β/IL-1R signalling with accelerated tubular cell senescence/arrest, with proximal tubular cells being the predominant senescent cell type." (PMID 39890773, 2025). "Another experimental study in IL-1Ra-deficient mice implicated exaggerated IL-1β signaling in progression of CKD and anemia by showing that an antibody targeting IL-1β was able to ameliorate the kidney damage and improve the response to hypoxia." (PMID 40486517, 2025). "In this context, pharmacological inhibitors of IL-1β receive increasing attention as tools bearing potential to alleviate immune-mediated kidney damage and preserve the functional renal architecture." (PMID 40486517, 2025). "Increased TNF-α levels in cisplatin-induced kidney damage are accompanied by rises in IL-8, IL-1β, and IL-18, further promoting inflammation and damage." (PMID 39599345, 2024). "Relative expression of IL‐6, MCP‐1, IL‐1β, and TNF‐α mRNA were significantly increased in kidney tissue, AND the levels of IL‐1β and p‐p65 were increased in adriamycin‐induced nephropathy rats." (PMID 37382268, 2023). "As a pathogen-associated molecular pattern, uric acid can cause the activation of NLRP3 inflammasome and subsequent release of IL-1β and IL-18 and lead to severe kidney damage." (PMID 35309342, 2022). "The present results are consistent with these findings, as the TRPV1 hyperfunction is associated with activation of inflammatory signals triggering IL-1β release in hyperoxaluria-induced nephropathy." (PMID 34201387, 2021). "Inhibition of NLRP3 inflammasome activation by silencing NLRP3/ASC or repressing caspase-1 activity has been shown to decrease the production of IL-1β and alleviate kidney damage." (PMID 34504642, 2021). "Local renal inflammation and thus kidney damage is further aggravated by the release of IL-1β from inflammatory cells upon inflammosome activation." (PMID 34064989, 2021). "In LPS-induced nephropathy, isolated podocytes exhibited a strong increase of IL-1β, confirming these findings in an unrelated in vivo model of FSGS." (PMID 30921378, 2019). "In this study, we demonstrated that treatment with an ADORA3 antagonist provides a renoprotective effect during the early stages of kidney damage in STZ-induced diabetic rats by decreasing the proinflammatory cytokines IL-1β and IL18." (PMID 31540220, 2019). "Blockade of IL-1β and NLRP3 inflammasome activation by IL-1Ra significantly attenuated renal tubular injury and function loss in AA-induced nephropathy." (PMID 31616439, 2019). "IL-1β has been described as a chemoattractant that recruits leukocytes to the areas of renal inflammation, which leads eventually to kidney damage." (PMID 29643981, 2018). "While serum levels of IFN-γ, IL-2, IL-4, and IL-12 did not display a difference between experimental groups (data not shown), expression of IL-5, IL-6, TNF-α, IL-10, CXCL1, and IL-1β was elevated in the NZM2410/J mice displaying signs of severe kidney damage." (PMID 28491039, 2017).
kidney damage (continued). "Thus, exaggerated IL-1β production and release by IL-1R1-deficient myeloid cells in response to multiple pro-inflammatory stimuli other than IL-1β aggravated the kidney damage in mouse AKI model." (PMID 40486517, 2025). "Therefore, compounds with anti‐inflammatory properties that target cytokines like TNF‐α and IL‐1β are known to reduce kidney damage due to IRI." (PMID 40025781, 2025). "For example, NF-κB is a pleiotropic transcription factor that regulates the expression of many genes involved in the inflammatory response during kidney injury and induces the release of proinflammatory cytokines such as TNF-α, IL-6, and IL-1β, which exacerbate kidney damage." (PMID 40607026, 2025). "Therefore, the present study was designed to evaluate the nephroprotective effect of diosmin against cisplatin-induced kidney damage by modulating IL-1β, IL-6, TNFα and renal oxidative damage in rats." (PMID 36770968, 2023). "The paracetamol-induced expression of IL-1β and IL-33 was also reduced upon chrysin pretreatment, suggesting that the anti-inflammatory effect of chrysin poses a beneficial therapeutic potential against paracetamol-induced kidney damage." (PMID 36552226, 2022). "In accordance with human reports, the present study and our previous studies showed that renal tubular inflammatory injuries were present in TCE-induced kidney damage, as evidenced by renal pathological examination and overexpression of IL-1β and IL-18 in renal tubules." (PMID 35656289, 2022). "As observed in the present study, increased NF-κB expression was accompanied by an increase in TNF-α and IL-1β expressions, and a decrease in IL-10, which is anti-inflammatory, suggestive of the involvement of inflammation in the pathogenesis of nephropathy in the untreated diabetic rats." (PMID 34198937, 2021). "Our data indicated that IL-1β could be another factor that augments Th17 differentiation and worsens kidney damage in the B6.Nrf2−/−lpr/lpr mice." (PMID 27941837, 2016). "The elevated IL-1β and IL-18 levels are observed in diabetic patients with nephropathy." (PMID 22701621, 2012). "Suppression of IL-1β has been further shown to attenuate CKD progression in obese and diabetic db/db mice as reflected by milder GFR decline and reduced renal expression of kidney damage biomarkers including the neutrophil gelatinase-associated lipocalin (NGAL)." (PMID 40486517, 2025). "Indirect suppression of IL-1β signaling by a caspase 1 inhibitor belnacasan (also known as VX-765) has been shown to ameliorate kidney damage and fibrosis in experimental AKI and CKD models but these beneficial effects may be also related to inhibition of pyroptosis." (PMID 40486517, 2025). "However, IL-6 expression was decreased in the kidney, similar to the observation for IL-1β; this may also help alleviate kidney damage." (PMID 33647718, 2021). "Thus, during metabolic endotoxemia, a large amount of lipopolysaccharide from the intestine that goes into the blood may activate the renal NLRP3 inflammasome, resulting in the release of IL-1β and promotion of kidney damage." (PMID 26881256, 2016). "it kickstarts the production of inflammatory mediators like TNF-α, IL-1β, and MCP-1, which fuel inflammation and worsen kidney damage." (PMID 41368583, 2025). "CaOx can induce kidney damage and stone deposition by triggering the formation of GSDMD-N mediated membrane pores and the release of IL-18 and IL-1β via activation of the NLRP3 inflammasome." (PMID 40384863, 2025). "Pro-inflammatory cytokines like IL-1β and TNF-α further drive kidney damage by increasing ferritin expression and disrupting iron balance." (PMID 41445831, 2025). "The study found that WIT effectively reduced renal MPO activity and NF-kB, IL-1β, TNF-α, and IL-6 levels in DOX-induced kidney damage." (PMID 40006061, 2025).
kidney damage (continued). "In a rat model of rhabdomyolysis-induced acute renal damage, PTX improved the renal function markers and attenuated the pathological signs of kidney damage by dampening the TLR4/NF-κB pathway and the expression of IL-1β and TNF-α." (PMID 38931349, 2024). "Proinflammatory cytokines, including IL-1β, TNF-α, and IL-6, are mediators of kidney injury, and the downregulation of inflammatory cytokines supported strain 44XBT-induced alleviation of kidney damage." (PMID 38814072, 2024). "Recent studies correlated the overexpression of pro-inflammatory (IL-1β, IL-6, TNF-α, and VEGF) and profibrotic genes (ICAM-1 and VCAM-1) with the appearance of nephropathies in diabetic patients." (PMID 36139749, 2022). "The increase in ALPK1, mainly in diabetic animal and human kidney cell models, leads to accelerated fibrotic nephropathy by enhancing the production of renin, TGF-β1, and IL-1β." (PMID 36139553, 2022). "Consistently, our previous studies also found an increase of various proinflammatory cytokines, including TNF-α, IL-1β, IL-17, and IL-6, in TCE-hypersensitivity induced kidney damage." (PMID 34393767, 2021). "NF-κB is a transcription factor that induces the production of proinflammatory factors, such as IL-1β and TNF-α and subsequent kidney damage." (PMID 33551679, 2021). "In contrast, serum murine IL-1β and IL-8 levels were remarkably downregulated in AAN after IL-22 intervention, suggesting systemic anti-inflammatory effects of IL-22 in AA-induced nephropathy." (PMID 31616439, 2019). "Additionally, 5-FU triggered crosstalk between Nrf2 and NF-κB/p38MAPK axis by significantly upregulating p-p38, p-JNK, p-ERK1/2, p-NF-κB, TNF-α, IL-1β, TGF-β, and IL-6, while downregulating Nrf2 and HO-1, resulting in kidney damage." (PMID 40492124, 2025). "Moreover, EST exhibited an additional ability to decrease the expression of IL-1β and TNF-α, underscoring its potential to suppress the inflammatory response and offering protection against PO-induced kidney damage." (PMID 38540830, 2024). "Similarly, apigenin has been demonstrated to reduce IL-6, TNF-α, and IL-1β levels, and increase IL-10 levels in the kidneys or serum in doxorubicin-induced male nephropathy BALB/c mice or in furan-induced nephropathy mice." (PMID 36422572, 2022). "In vivo experiments in mice showed that APS can reverse LPS-induced kidney damage in a concentration-dependent manner (P < 0.05); the concentrations of BUN and Scr were increased (all P < 0.05); similarly, the levels of TNF-α and IL-1β were increased as well (all P < 0.05)." (PMID 33575163, 2021). "Studies have suggested that a persistent inflammatory response mediated by pro-inflammatory cytokines such as interleukin 1 beta (IL-1β), interleukin 6 (IL-6) and tumor necrosis factor alpha (TNF-α) contributes to the perpetuation of kidney damage (Furuichi, Kaneko & Wada, 2009)." (PMID 31275747, 2019). "In the present study, an elevation of the serum values of IL-1β, IL-6 and TNF-α was observed as the degree of renal damage induced by FA progressed; this is consistent with the histological findings of an increase in inflammatory infiltrates as the degree of kidney damage increased." (PMID 31275747, 2019). "B4 could suppress the expression of IL-6, IL-1β, and NFκB but had a negative effect on TNFα expression, indicating that the anti-inflammatory effects of B4 on adenine-induced kidney damage are related to IL-6 and IL-1β/NFκB signaling." (PMID 31275420, 2019). "A study, comparing the inflammation status in DM with/without nephropathy, demonstrated that plasma levels of proinflammatory monocytes as well as circulatory inflammatory mediators, such as PAI-1, syndecan-1, VEGF, IL-1β, IL-1Ra, and CCL4, increased in nephropathy subjects." (PMID 34941711, 2021).
kidney damage (continued). "Levels of adiponectin were higher in patients with nephropathy (21.84 ± 8.15 vs 14.88 ± 8.27 mg/ml, p = 0.008), but not regarding the presence of retinopathy; neither TNF- α, nor IL-6 and IL-1β showed differences regarding the presence of microvascular disease." (PMID 26382922, 2015).
ovarian carcinoma (65 papers, 1992 to 2026). A malignant neoplasm originating from the surface ovarian epithelium. "Our study only explored the effects of IL-1β on ovarian cancer cell lines, and its effects on tumor-associated macrophages and fibroblasts, as well as in vivo experiments and clinical analyses, need to be further studied." (PMID 40244135, 2025). "The matrix metalloproteinase MMP8 is associated with cancer progression, and IL-1β can induce MMP8 expression in 2780 ovarian cancer cell lines." (PMID 40244135, 2025). "TNF-α and IL-1β induced SPATA2 expression in ovarian cancer cells and that increased SPATA2 expression was associated with poor prognosis of ovarian cancer patients." (PMID 35754839, 2022). "Finally, IL1B was found to be significantly upregulated in ovarian cancer tissues based on GEO database analyses and was associated with advanced stage and poor grade." (PMID 41029721, 2025). "IL-1β/β1-integrin axis is implicated in ovarian cancer cell adhesion to mesothelial cells." (PMID 32780245, 2020). "Furthermore, because the frequency of IL-1β expression in human ovarian cancer specimens was strongly associated with overall survival, it is possible that IL-1β may also serve as a biomarker for prognosis or as a monitoring biomarker for therapeutic response." (PMID 22296757, 2012). "Stable overexpression of IL-1β in ovarian cancer cells inhibited growth and metastasis, while its knockdown in A2780 cells promoted cell activity and metastasis." (PMID 40244135, 2025). "In this study, we found that the expression of interleukin-1β (IL-1β), a proinflammatory cytokine, increased in an ovarian cancer tissue microarray (TMA) and inhibited A2780 and SKOV3 cell viability and metastasis." (PMID 40244135, 2025). "In turn, IL-1β binds to IL-1R on ovarian cancer cells, activating the NF-κB pathway and further stimulating SAA1 production." (PMID 41029721, 2025). "Overall, we found that the proinflammatory cytokine IL-1β inhibits ovarian cancer cell viability and metastasis." (PMID 40244135, 2025). "The results revealed that the IL-1β level was higher in the ovarian cancer cells compared to the control cells." (PMID 40244135, 2025). "The results showed that the concentration of IL-1β is higher in patients with ovarian cancer compared to the concentration of this interleukin in healthy women (p=0.040)." (PMID 41561739, 2025). "The signaling pathway involving MAPK/AP-1/MMP12 is involved in IL-1β-regulated ovarian cancer progression." (PMID 40244135, 2025). "This study revealed that the average urinary IL-1β in patients with ovarian benign and ovarian cancer is higher than that in healthy individuals." (PMID 40244135, 2025). "In contrast, examination of IL-1Ra levels in the peritoneal fluid of patients diagnosed with ovarian cancer showed statistically significantly higher IL-1β levels among women in stage G3 vs. G1 (p<0.001) and G3 vs. G2 (p<0.01)." (PMID 41561739, 2025). "Lastly, the therapeutic efficacy of targeting SAA1 and IL-1β in ovarian cancer immunotherapy warrants further comprehensive investigation." (PMID 41029721, 2025). "This secreted IL-1β further amplifies SAA1 expression in ovarian cancer cells through IL-1R/NF-κB signaling, thereby forming a positive feedback loop that reinforces a tumor-promoting immunosuppressive microenvironment conducive to immune evasion." (PMID 41029721, 2025). "The application of the NF-κB pathway inhibitor APDC markedly suppressed IL-1β-induced SAA1 secretion in ovarian cancer cells." (PMID 41029721, 2025). "Subsequently, transwell assays were conducted to study the role of recombinant IL-1β in the metastasis of ovarian cancer." (PMID 40244135, 2025).